CHRDL2 (chordin like 2)
Description:
May inhibit BMPs activity by blocking their interaction with their receptors. Has a negative regulator effect on the cartilage formation/regeneration from immature mesenchymal cells, by preventing or reducing the rate of matrix accumulation (By similarity). Implicated in tumor angiogenesis. May play a role during myoblast and osteoblast differentiation, and maturation.
Synonyms: BNF1; CHL2
Tractability: Antibody: UniProt places it where antibodies can reach, with high confidence; UniProt predicts a signal peptide or a membrane-spanning region; its Gene Ontology location is reachable by antibodies, with medium confidence.
Gene: Protein-coding gene on chromosome 11 (74,696,429 to 74,731,426, reverse strand). Ensembl gene ENSG00000054938.
Subcellular location: Secreted (Isoform 1); Secreted (Isoform 2); Cytoplasm (Isoform 3); Cytoplasm (Isoform 4); Cytoplasm (Isoform 5)
Subcellular location (Human Protein Atlas): Vesicles; Predicted to be secreted
Gene Ontology:
Molecular function: BMP binding
Biological process: cell differentiation; negative regulation of BMP signaling pathway; developmental process
Cellular component: extracellular region; cytoplasm
Genetic constraint (gnomAD): Loss-of-function variants: 38 observed, 50.11 expected, observed/expected ratio (o/e) 0.76, 90% interval 0.58 to 0.99. The upper end of that interval is the gene's LOEUF score, 0.99, which puts it in group 4 of 6, group 1 being the genes least tolerant of losing a copy. Missense variants: 505 observed, 553.87 expected, observed/expected ratio (o/e) 0.91, 90% interval 0.85 to 0.98. Synonymous variants: 217 observed, 226.14 expected, observed/expected ratio (o/e) 0.96, 90% interval 0.86 to 1.07.
Homologues: Orthologues: macaque CHRDL2 (98% identical), dog CHRDL2 (90% identical), chimpanzee CHRDL2 (88% identical), rabbit CHRDL2 (84% identical), pig CHRDL2 (79% identical), guinea pig CHRDL2 (74% identical), mouse Chrdl2 (72% identical), rat Chrdl2 (69% identical), tropical clawed frog chrdl2 (58% identical). Paralogues in human: CHRDL1 (38% identical), MUC5B (25% identical), MUC5AC (24% identical), OTOG (23% identical), VWF (23% identical), FCGBP (22% identical), OTOGL (22% identical), MUC2 (20% identical), MUC6 (20% identical), ZAN (19% identical), MUC19 (18% identical), KCP (17% identical), and 7 more.